Y_RNA (Y RNA )
Gene: Miscellaneous RNA gene on chromosome 10 (6,245,731 to 6,245,831, reverse strand). Ensembl gene ENSG00000238366.
Homologues: Orthologues: chimpanzee Y_RNA (99% identical), macaque Y_RNA (95% identical), guinea pig Y_RNA (89% identical). Paralogues in human: Y_RNA (91% identical), RNY3 (89% identical), Y_RNA (89% identical), RNY3P1 (88% identical), Y_RNA (88% identical), Y_RNA (87% identical), Y_RNA (86% identical), Y_RNA (85% identical), RNY3P11 (84% identical), RNY3P14 (84% identical), RNY3P16 (84% identical), Y_RNA (84% identical), and 97 more.